CLDN2 (claudin 2)
Diseases named in the same sentence as CLDN2 in open-access papers (continued):
Sharing a sentence is not in itself a finding about the gene and the disease.
breast carcinoma (continued). "The model’s validity was further verified using breast cancer cells overexpressing metastasis-specific genes (CXCR4, claudin-2, Linc-ZNF469-3) and a patient-derived organoid (PDO) from a patient with advanced metastatic disease." (PMID 40510151, 2025). "Therefore, KK-LC-1 may regulate breast cancer liver metastasis through CLDN2." (PMID 36895039, 2023). "CLDN2, 3, and 4 have been reported to be decreased by short peptides, which mimic ECL2 of each CLDN, in lung adenocarcinoma and breast cancer cells." (PMID 32824620, 2020). "Given the implication of these results for the treatment of breast cancer patients with pan-SFK inhibitors, we next investigated the involvement of individual SFK members (c-Src, Fyn, Yes or Lyn) in the regulation of Claudin-2 expression." (PMID 25823815, 2015). "We have employed triple negative breast cancer models, expressing Claudin-2 (MDA-MB-231 and BRC31), to elucidate the role of Claudin-2 as a promoter of the breast cancer liver metastatic phenotype." (PMID 25823815, 2015). "Compared to breast cancer patients without liver metastases, CLDN2 expression in the primary tumor of breast cancer patients with liver metastases was significantly increased." (PMID 36895039, 2023). "In contrast, reduction of Pdlim2 expression failed to negatively impact the growth of liver-aggressive breast cancer cells in soft agar, suggesting that this candidate was not important for Claudin-2-mediated anchorage-independent growth." (PMID 30692208, 2019). "No significant change in the growth of mammary tumors was observed between parental (2776p), empty vector, knockdown, pooled wild-type (Cldn2 wild-type), or pooled mutant 4T1 populations (Cldn2 ΔPDZ BD)." (PMID 30692208, 2019). "Thus, in the context of breast cancer cells, the dominant effect of PP2 or Dasatinib appears to be mediated through the inhibition of Yes or Fyn activity, which leads to higher Claudin-2 expression." (PMID 25823815, 2015). "However, the involvement of the PDZ-binding motif of Claudin-2 in breast cancer metastasis to the liver is not currently known." (PMID 30692208, 2019). "Together, these observations argue that the Claudin-2 ΔPDZ BD mutant may not function as a dominant negative to promote breast cancer liver metastasis." (PMID 30692208, 2019). "In the present study, we analysed the possible relationship of claudin-2, -3, -4, -6, -7, and -17 expression and VM formation in two breast cancer cell lines, aggressive MDA-MB-231 and non-aggressive MCF-7 cells, and the human umbilical vein endothelial cell line (HUVEC)." (PMID 25871476, 2015). "Interestingly, mice injected with 2776 breast cancer cells harboring Claudin-2 targeting shRNAs failed to exhibit an elevated liver metastatic burden in response to Dasatinib treatment." (PMID 25823815, 2015).
lung adenocarcinoma (30 papers, 2009 to 2026). A carcinoma that arises from the lung and is characterized by the presence of malignant glandular epithelial cells. "We need further study to clarify the mechanism underlying CLDN2-induced chemoresistance in lung adenocarcinoma." (PMID 34205320, 2021). "Claudin-2 (CLDN2), an integral membrane protein located at tight junctions, is abnormally expressed in human lung adenocarcinoma tissues, and is linked to drug resistance in human lung adenocarcinoma A549 cells." (PMID 33419064, 2021). "Claudin-2 is highly expressed in lung adenocarcinoma and is linked to increased tumor cell proliferation, and another study in the same year also concluded that decreased claudin-2 hinders lung carcinoma development." (PMID 33262947, 2020). "The nuclear localization of claudin-2 and claudin-6 has been linked to enhanced cell proliferation via promotion of cell cycle progression in lung adenocarcinoma cells." (PMID 31717460, 2019). "It is known that CLDN-2 also contributes to the cell proliferation and chemoresistance of lung adenocarcinoma." (PMID 38338691, 2024). "The downregulation of angulin-1/LSR induces the malignancy of lung adenocarcinoma via EGF-dependent CLDN-2 and TGF-β-dependent cell metabolism." (PMID 38338691, 2024). "In lung adenocarcinoma, CLDN-2 exhibits high expression through an EGFR/MEK/ERK/c-Fos pathway, and its overexpression has been linked to increased proliferation." (PMID 38338691, 2024). "It was found that the downregulation of CGN induced malignancy via upregulation of MEK-dependent CLDN-2, cell metabolism and cell migration in human lung adenocarcinoma A549 cells." (PMID 38338691, 2024). "In conclusion, AG1478 and EW-7197 demonstrated potent in vitro anti-lung adenocarcinoma therapeutic activities via LSR/CLDN-2 and the cell metabolism." (PMID 36961882, 2023). "Among others, the specific Claudin-2 protein, in turn, is involved in neoplastic proliferation and is highly expressed in human lung adenocarcinoma cells." (PMID 36840233, 2023). "Abnormal expression of bicellular tight junction claudins, including claudin-2 are observed during carcinogenesis in human lung adenocarcinoma." (PMID 36961882, 2023). "In the lung adenocarcinoma tissues examined in the present study, expression of claudin-2 was higher than in normal lung tissues, while angulin-1/LSR was poorly or faintly expressed." (PMID 36961882, 2023). "In human lung adenocarcinoma cells, downregulation of the tricellular tight junction molecule angulin-1/LSR causes malignancy via EGF-dependent CLDN-2 and TGF-dependent cellular metabolism." (PMID 38001653, 2023). "In human lung adenocarcinoma cells, CLDN-2 knockdown decreases matrix metalloproteinase-9 activity and cell migration via suppression of nuclear Sp1." (PMID 36961882, 2023). "CLDN-2 is highly expressed in lung adenocarcinoma tissues and increases proliferation in adenocarcinoma cells." (PMID 36961882, 2023). "Here, we found that coffee ingredients, namely caffeine and theobromine, decreased the protein level of CLDN2 in human lung adenocarcinoma-derived A549 cells." (PMID 36555089, 2022). "The effects of caffeine on CLDN2 expression and anticancer-drug-induced toxicity were also observed in lung adenocarcinoma RERF-LC-MS cells." (PMID 36555089, 2022). "CLDN2 is highly expressed in human solid tumors, including lung adenocarcinoma, colon, liver, and stomach cancers." (PMID 36555089, 2022). "Cell proliferation is suppressed by the silencing of CLDN2 expression in human lung adenocarcinoma A549 and colon cancer Caco-2 cells." (PMID 36555089, 2022). "CLDN2 is highly expressed in human lung adenocarcinoma A549, RERF-LC–MS (JCRB0081, JCRB Cell Bank), and PC-3 (JCRB0077, JCRB Cell Bank) cells and involved in the regulation of cell proliferation, migration, and anticancer drug toxicity." (PMID 35886884, 2022).
lung adenocarcinoma (continued). "We previously reported that CLDN2 expression is upregulated in the malignant tissues and cell lines derived from human lung adenocarcinoma." (PMID 35886884, 2022). "The downregulation of CLDN2 expression by siRNA inhibits proliferation and migration in monolayer culture model of human lung adenocarcinoma A549 cells." (PMID 35886884, 2022). "Downregulation of claudin-2 suppressed the proliferation and migration of lung adenocarcinoma cells." (PMID 35656022, 2022). "We found that coffee ingredients, namely caffeine and theobromine, can decrease the protein level of CLDN2 in human lung adenocarcinoma A549 cells." (PMID 36555089, 2022). "CLDN2 is involved in the upregulation of proliferation, migration, and chemoresistance in human lung adenocarcinoma cells." (PMID 36555089, 2022). "Our data suggest that C3G-rich foods can prevent the chemoresistance of lung adenocarcinoma A549 cells through the reduction of CLDN2 expression." (PMID 33419064, 2021). "This is the first report demonstrating that CLDN2 expression is reduced by C3G in lung adenocarcinoma A549 cells." (PMID 33419064, 2021). "Our study suggests C3G to be a useful food component in preventing CLDN2-induced chemotherapy resistance in lung adenocarcinoma A549 cells." (PMID 33419064, 2021). "So far, we have reported that CLDN2 is highly expressed in human lung adenocarcinoma tissues and cell lines." (PMID 34205320, 2021). "The knockdown of CLDN2 expression by siRNA induces the inhibition of proliferation and migration in human lung adenocarcinoma A549 cells." (PMID 34205320, 2021). "So far, we reported that CLDN2, which is highly expressed in human lung adenocarcinoma tissues and cell lines, induces chemoresistance against anticancer drugs including DXR, cisplatin, and docetaxel in A549 spheroid cells." (PMID 34205320, 2021). "The HDAC inibitors trichostatin A (TSA) and Quisinostat (JNJ-2648158) increase angulin-1/LSR, decrease CLDN-2, promote G1 arrest and prevented the migration of lung adenocarcinoma A549 cells." (PMID 34944960, 2021). "We recently reported that the expression of CLDN2 is increased in human lung adenocarcinoma tissues and adenocarcinoma-derived cultured cells, including A549." (PMID 32340376, 2020). "We have reported that abnormal expression of CLDN2 confers chemoresistance in the spheroids of human lung adenocarcinoma A549 cells." (PMID 32340376, 2020). "We recently reported that both VPDSM and DSMKF, with structures that are not similar to the ECL2 of CLDN3 and CLDN4, decrease the protein level of CLDN2 and enhance chemosensitivity of in vitro spheroids of lung adenocarcinoma cells." (PMID 32824620, 2020). "A role of claudin-2 in proliferation has been also suggested in studies with lung adenocarcinoma cells." (PMID 31783547, 2019). "In contrast, according to one study, two-thirds of examined lung adenocarcinoma samples overexpressed claudin-2." (PMID 31726679, 2019). "In A549 lung adenocarcinoma cells, ephrinA1 reduced both claudin-2 expression and proliferation, and both were mediated by Cdx-2." (PMID 31726679, 2019). "Here, we found that kaempferol, chrysin, and luteolin decrease the mRNA and protein levels of claudin-2 in lung adenocarcinoma A549 cells." (PMID 28608828, 2017). "We previously reported that quercetin decreases claudin-2 expression in human lung adenocarcinoma A549 cells." (PMID 28608828, 2017). "We found that flavonoids including kaempferol, chrysin, and luteolin concentration-dependently decrease claudin-2 expression in lung adenocarcinoma A549 cells." (PMID 28608828, 2017). "We have been reported that the expression of claudin-2 is up-regulated in human lung adenocarcinoma tissues." (PMID 28608828, 2017). "CLDN2 expression in lung adenocarcinoma tissue is higher than that in normal tissue and other lung carcinomas." (PMID 28160565, 2017). "Claudin-2 is highly expressed in human lung adenocarcinoma tissues and A549 cells compared with that in the normal lung tissue." (PMID 26061016, 2015).
lung adenocarcinoma (continued). "The EGFR-MEK-ERK1/2 pathway has been implicated in the transcriptional regulation of CLDN2 in A549 lung adenocarcinoma cells through binding of the transcription factors, c-Fos and c-Jun, to the human CLDN2 promoter region via an AP-1 binding site." (PMID 25823815, 2015). "Using reporter assays and chromatin immunoprecipitation approaches, it has recently been shown that the EGFR-MEK-ERK1/2 pathway can regulate the transcription of CLDN2 in A549 lung adenocarcinoma cells." (PMID 25823815, 2015). "We here found that quercetin, a flavonoid present in fruits and vegetables, time- and concentration-dependently decreases claudin-2 expression in lung adenocarcinoma A549 cells." (PMID 26061016, 2015). "The expression of claudin-1 and -7 is up-regulated and that of claudin-2 is down-regulated in human lung adenocarcinoma." (PMID 26061016, 2015). "In this present study, our findings indicate that the downregulation of CGN and FOXO1 leads to malignant cell proliferation, cell migration, and altered cell metabolism by upregulating CLDN-2 or CLDN-4 through the MAPK/AMPK pathways in human lung adenocarcinoma A549 cells." (PMID 38338691, 2024). "It is possible that CLDN-2 may be highly expressed in the carcinogenesis of lung adenocarcinoma and LSR may be highly expressed in well-differentiated cancers and then may decrease in poorly differentiated cancers." (PMID 36961882, 2023). "To investigate whether knockdown of CLDN-2 affected cell proliferation, cell migration and cell metabolism in lung adenocarcinoma, we performed knockdown of CLDN-2 using the siRNA of CLDN-2 and examined the cell cycle, cell migration and cell metabolism." (PMID 36961882, 2023). "Furthermore, inhibition of cell proliferation in lung adenocarcinoma is partly related to the decrease in CLDN2 expression upon treatment with the DNA methyltransferase inhibitor azacitidine (AZA)." (PMID 36672179, 2023). "CLDN-2 expression is increased via an EGFR/MEK/ERK/c-Fos pathway in lung adenocarcinoma A549 cells." (PMID 36961882, 2023). "Therefore, it is important to develop food ingredients and drugs that can inhibit stress response and/or decrease CLDN2 expression in lung adenocarcinoma cells." (PMID 36555089, 2022). "CLDN2 is highly expressed in human lung adenocarcinoma and liver cancer cells." (PMID 36555089, 2022). "CLDN2 contributes to chemoresistance in human lung adenocarcinoma-derived A549 cells, and it may be a target for cancer therapy." (PMID 36555089, 2022). "This is the first report showing that caffeine can reduce CLDN2 expression in lung adenocarcinoma." (PMID 36555089, 2022). "Claudin-2 was upregulated in human lung adenocarcinoma tissues." (PMID 35656022, 2022). "Similarly, the mRNA levels of glucose transporters, metabolic enzymes, and Nrf2-targeted genes were decreased by CLDN2 knockdown in spheroids of human lung adenocarcinoma PC-3 cells." (PMID 34205320, 2021). "We previously reported that the expression level of CLDN2 is increased in human lung adenocarcinoma tissues, and is involved in the increased proliferation, migration, and drug-resistance of human lung adenocarcinoma A549 cells." (PMID 33419064, 2021). "CLDN2 may be a target for the prevention of lung adenocarcinoma, but there are few compounds which can reduce CLDN2 expression." (PMID 33419064, 2021). "Furthermore, downregulation of angulin-1/LSR induces malignancy via EGF-dependent CLDN-2 in a human lung adenocarcinoma cells." (PMID 34944960, 2021). "Therefore, it is necessary to clarify the effect of C3G on CLDN2 expression using other lung adenocarcinoma cell lines and/or animal models in a further study." (PMID 33419064, 2021). "These intracellular signaling pathways may be useful to search for compounds that can reduce CLDN2 expression in lung adenocarcinoma cells." (PMID 32340376, 2020). "Moreover, claudin-2 has been found localized at the nuclear fractions in highly proliferative lung adenocarcinoma cells." (PMID 31783547, 2019).
lung adenocarcinoma (continued). "Indeed, EGFR signaling is key in upregulating claudin-2 in the human lung adenocarcinoma cell line A549." (PMID 31726679, 2019). "Ikari recently reported that CLDN2 enhances cell colonization and migration in lung adenocarcinoma cell line A549, and CLDN2 may be involved in the regulation of cancer cell motility." (PMID 28160565, 2017). "Claudin-2 is highly expressed in human lung adenocarcinoma tissues and may be a novel target for cancer chemotherapy because knockdown of claudin-2 decreases cell proliferation." (PMID 28608828, 2017). "Claudin-2 is highly expressed in human lung adenocarcinoma tissues and cells." (PMID 26061016, 2015). "Furthermore, quercetin decreased the expression level of claudin-2 mRNA in lung adenocarcinoma cell lines such as PC-3 and ABC-1." (PMID 26061016, 2015). "Our results indicate that quercetin may decrease claudin-2 expression through increasing miR-16 expression in lung adenocarcinoma cells." (PMID 26061016, 2015). "Notably, claudin 2 was selectively expressed in lung adenocarcinomas, whereas claudin 5 expression was strongly repressed in lung tumors." (PMID 19812696, 2009). "Additionally, CLDN2 displays elevated expression in human lung adenocarcinoma cells and contributes to enhanced cell proliferation, while its knockdown has been shown to increase paracellular permeability and intracellular accumulation of doxorubicin in tumor spheroids." (PMID 41399659, 2026). "Therefore, CLDN2 may confer chemoresistance to lung adenocarcinoma cells mediated through other mechanisms." (PMID 34205320, 2021). "However, the effects of C3G on the chemosensitivity and the CLDN2 protein in lung adenocarcinoma cells remain unclear." (PMID 33419064, 2021). "Therefore, CLDN2 may be one of the therapeutic targets for anticancer therapy, but there are few compounds that can reduce CLDN2 expression in lung adenocarcinoma cells." (PMID 32340376, 2020). "We recently reported that CLDN2 may be involved in the development of lung adenocarcinoma." (PMID 32340376, 2020). "The downregulation of angulin-1/LSR induces malignancy via the upregulation of EGF-dependent CLDN-2 and cell metabolism via TGF-β signaling that induces EMT in lung adenocarcinoma." (PMID 38338691, 2024). "We previously reported that the class I and II HDAC inhibitors TSA and Quisinostat (JNJ) have potential for use in therapy for lung adenocarcinoma via changes in the expression of angulin-1/LSR and CLDN-2." (PMID 38338691, 2024). "The loss of angulin-1/LSR promotes the malignancy via EGF-dependent CLDN-2 and TGF-β-dependent cell metabolism in human lung adenocarcinoma." (PMID 38338691, 2024). "In conclusion, downregulation of angulin-1/LSR induces malignancy via EGF-dependent claudin-2 and TGF-β-dependent cell metabolism in human lung adenocarcinoma." (PMID 36961882, 2023). "In the present study, the EGFR tyrosine kinase inhibitor AG1478 prevented the upregulation of CLDN-2 at the protein and mRNA levels induced by EGF in lung adenocarcinoma cell line A549." (PMID 36961882, 2023). "TSA and Quisinostat have the potential to be used in the treatment of lung adenocarcinoma by altering the expression of angulin-1/LSR and CLDN-2." (PMID 38001653, 2023). "CLDN2, on the other hand, was described to increase the mRNA level and enzymatic activity of MMP-9 through elevating Sp1 nuclear distribution in the human lung adenocarcinoma cell line A549." (PMID 36672179, 2023). "In the present study, we found that downregulation of angulin-1/LSR induced malignancy via upregulation of EGF-dependent CLDN-2 and TGF-β-dependent cell metabolism in human lung adenocarcinoma." (PMID 36961882, 2023). "Therefore, CLDN2 may be a novel target for reversing chemoresistance in lung adenocarcinoma." (PMID 35886884, 2022). "Claudin-2 (CLDN2), a component of tight junctions, is abnormally expressed in human lung adenocarcinoma tissue." (PMID 36555089, 2022).